FGFR3 (fibroblast growth factor receptor 3)
Diseases named in the same sentence as FGFR3 in open-access papers (continued):
Sharing a sentence is not in itself a finding about the gene and the disease.
urothelial carcinoma (continued). "The fact that even a genetic alteration as prevalent as FGFR3 mutation is by itself incapable of causing urothelial carcinoma in vivo, as we demonstrated here, illustrates the need to validate the molecular profiling data from human tumors using experimental systems." (PMID 27157475, 2016). "Uromonitor® is a quantitative PCR-based assay targeting hotspot variants in the TERT promoter, FGFR3, and KRAS, which are frequently altered in urothelial carcinoma." (PMID 42193009, 2026). "Taken together, it is remarkable that most FGFR3::TACC3 fusion carcinomas display either a transitional cell-like morphology (including urothelial carcinoma), a squamous cell phenotype (SCC), or combined features of both." (PMID 39387893, 2025). "Luminal-papillary tumors, enriched for FGFR3 alterations, are sensitive to FGFR inhibitors such as erdafitinib, which has shown clinical benefit in FGFR3-mutant urothelial carcinoma." (PMID 40698358, 2025). "In patients with FGFR3-altered urothelial carcinoma, erdafitinib achieved an objective response rate (ORR) of 40%, markedly outperforming chemotherapy, which yielded an ORR of 13%." (PMID 41514604, 2025). "The US FDA has recently approved FGFR inhibitors, such as erdafitinib, as effective therapeutic options for FGFR3 altered urothelial carcinoma (UC)." (PMID 41375830, 2025). "We studied the interaction of fibroblast growth factor receptor (FGFR) inhibition with ICI in urothelial carcinoma (UC) of the bladder, in which FGFR3 is altered in 50% of cases." (PMID 38226620, 2024). "FGFR3-mutant uroepithelial carcinoma (UC) exhibits a more immunosuppressive tumor microenvironment (TME) with lower immune cell infiltration and T-cell toxicity compared to FGFR3-wildtype UC." (PMID 38962005, 2024). "Evidence from existing studies with other FGFR-driven cancers, such as urothelial carcinoma and cholangiocarcinoma, demonstrates the efficacy of pemigatinib in tumors that are refractory to conventional chemotherapeutic agents, especially FGFR3 alteration." (PMID 38845691, 2024). "Patients with pure urothelial carcinoma (n = 18) and low FGFR3 showed significantly better response to EV than those with high FGFR3." (PMID 39408678, 2024). "Despite this, several studies have focused on FGFR-3 as therapeutic and prognostic marker in urothelial carcinoma." (PMID 37370778, 2023). "Compared with FGFR3-WT in urothelial carcinoma, FGFR3 alteration results in low expression of TGF-β and EMT signaling." (PMID 36966334, 2023). "FGFR3-mutant urothelial carcinomas have also been noted to possess an immune microenvironment background with increased T-cell exhaustion." (PMID 36966334, 2023). "The assessment of the mutational features has been the main objective of seminal studies shedding light on the frequency of FGFR3 alterations and other molecular features in urothelial carcinomas, focusing on localized diseases." (PMID 37377403, 2023). "Due to the rarity of FGFR3 fusions in prostate cancer, a workup for a second primary cancer was performed, leading to the diagnosis of an otherwise-asymptomatic urothelial carcinoma (UC)." (PMID 37980380, 2023). "As a result, the development of highly selective FGFR3 inhibitors is an area of interest in the treatment of urothelial carcinoma, and early Phase I trials of such agents are ongoing." (PMID 37296985, 2023). "In 11 of 19 patients (58%) with FGFR3-driven urothelial carcinoma, we detected an alteration in the PI3K–mTOR pathway in postprogression and/or in baseline samples." (PMID 37377403, 2023). "FGFR3 alterations are particularly important as they can be detected in about 18% of all urothelial carcinoma cases." (PMID 35456300, 2022).
urothelial carcinoma (continued). "Adult patients with histologically documented urothelial carcinoma, changes in the FGFR3 gene, and radiologically measurable tumors according to RECIST 1 were enrolled in the study." (PMID 35326568, 2022). "Patients with histologically proven urothelial carcinoma whose tumors were FGFR-1 or FGFR-3 positive and who had received at least one course of platinum-based chemotherapy in the past and whose disease had progressed were enrolled in the study." (PMID 35326568, 2022). "In urothelial carcinoma, FGFR3 alterations were found to be an early event, and were further identified as a prognostic factor in BC patients." (PMID 35958598, 2022). "FGFR3 functions corrupted by translocations are frequently observed in urothelial carcinoma and glioblastoma." (PMID 34732230, 2021). "Erdafitinib, a tyrosine kinase inhibitor (TKI) of FGFR, was approved by the USA FDA in April 2019 for advanced urothelial carcinoma with actionable FGFR2/FGFR3 alterations as the first molecularly targeted therapy." (PMID 34160364, 2021). "Compared to the high frequency of FGFR2 fusions in cholangiocarcinoma, FGFR3 fusions are more commonly detected in urothelial carcinoma and glioblastoma multiforme (GBM), with fewer cases detected in lung cancer." (PMID 34732230, 2021). "This profile translates into potentactivity in xenograft tumor models with translocations in FGFR1 (8p11-translocatedmyeloid leukemia), FGFR2 (cholangiocarcinoma), and FGFR3 (urothelial carcinoma)." (PMID 32315352, 2020). "Similar results were seen in cells engineered to express another common FGFR3 cysteine mutant found in urothelial carcinoma (R248C) and its glycine substituted mutant (R248G)." (PMID 32370101, 2020). "Targeting the Src pathway with low doses of the kinase inhibitor dasatinib synergistically sensitized multiple urothelial carcinoma lines harbouring endogenous FGFR3 alterations to infigratinib." (PMID 32370101, 2020). "Selective FGFR inhibitors such as infigratinib (BGJ398) and erdafitinib (JNJ-42756493) have been evaluated in clinical trials for cancers with FGFR3 molecular alterations, particularly in urothelial carcinoma patients." (PMID 32370101, 2020). "In this phase 2 study that enrolled 99 patients with advanced urothelial carcinoma carrying FGFR3 or FGFR2/3 genomic alterations, an RR of 40%, with 3% of patients obtaining a CR, was observed." (PMID 32962091, 2020). "The prevalence of FGFR3 gene aberrations is highest in urothelial carcinomas (18% of cases), followed by uterine carcinosarcoma (14%), esophageal (5%), ovarian (5%), and endometrial (4%) cancers." (PMID 33224141, 2020). "We find that targeting the Src pathway with low dose dasatinib sensitizes urothelial carcinoma cell lines harbouring endogenous FGFR3 molecular alterations to selective FGFR TKIs including infigratinib." (PMID 32370101, 2020). "In this study, we demonstrate that cells expressing cancer-associated activating FGFR3 mutants and the FGFR3-TACC3 fusion showed primary resistance to infigratinib in long-term colony formation assays in both NIH-3T3 and urothelial carcinoma models." (PMID 32370101, 2020). "This study was undertaken to analyze the immunohistochemical expression of fibroblast growth factor receptor (FGFR3) in urothelial carcinoma and correlate its expression with the pathological stage, recurrence and other clinicopathological parameters." (PMID 31528172, 2019). "miR-34a negatively regulates the cell cycle by reducing CCND1 (cyclin D1) and CDK4 (cyclin dependent kinase 4) levels; its downregulation promotes a more aggressive behavior of FGFR3 in urothelial carcinoma cases." (PMID 29165379, 2017). "MFGR1877S (Genentech) is a human anti-FGFR3 monoclonal antibody that demonstrated activity in preclinical models of urothelial carcinoma harboring FGFR3 overexpression." (PMID 28030802, 2017). "A mutation was detected in exon 10 (Y375C) of FGFR3, indicating a high probability (94.7% PPV) that the patient had urothelial carcinoma." (PMID 22873290, 2012).
urothelial carcinoma (continued). "Similarly, resistance to FGFR3 inhibitors in urothelial carcinoma can occur through activation of downstream signaling pathways." (PMID 41409251, 2025). "However, several studies have pointed out that most of FGFR3::TACC3 fusion–positive tumors represent either SCC or urothelial carcinomas with squamous-like phenotype." (PMID 39387893, 2025). "Hotspot mutations in the FGFR3 gene (R248C, S249F/C, G372C, and Y375C (missense gain-of-function mutations)) and upstream of the TERT promoter (C228T and C250T (gain-of-function mutations)) are often identified in urothelial carcinoma samples." (PMID 40722489, 2025). "In urothelial carcinoma, reduced miR-100 expression correlates with aberrant FGFR3 activation and enhanced downstream signaling, implicating the miR-100-associated non-coding RNA regulatory networks in modulating drug sensitivity and acquired resistance in FGFR-driven malignancies." (PMID 41514604, 2025). "A few groups have aimed to compare the FGFR3 status in primary urothelial carcinomas vs metastases." (PMID 41097827, 2025). "Erdafitinib, an FGFR inhibitor, is approved for FGFR3-altered urothelial carcinoma, and emerging agents targeting epigenetic alterations such as ARID1A or KMT2D mutations may expand future treatment options." (PMID 41395625, 2025). "The non-T-cell inflamed subtype of urothelial carcinoma with FGFR3 mutations was found to have low to absent CD8+ T-cells in the TME, resulting in resistance to ICI monotherapy." (PMID 38255923, 2024). "Moreover, recent preclinical data confirm that FGFR inhibition in FGFR3-mutant urothelial carcinoma abolishes immunosuppression and increases the efficacy of anti-PD-1 agents." (PMID 38674231, 2024). "In urothelial carcinoma, FGFR3 alterations have been previously documented in nearly 60% of low-grade noninvasive papillary urothelial carcinoma of the bladder, 35.6% of upper tract high-grade urothelial cancer, and 26.7% of overall urothelial carcinoma." (PMID 38255923, 2024). "Currently, based on the approval of erdafitinib for the indication of urothelial carcinoma, the FGFR RGQ RT-PCR assay kit (Qiagen) has been approved by the Food and Drug Administration (FDA) for the companion diagnostic testing of FGFR3 point mutations in urothelial carcinoma." (PMID 39583123, 2024). "The controversial manifestation of FGFR3 and PD-L1 in various stages of the examined cystectomic samples in our study suggest a deeper stratification in molecular and immunological status in urothelial carcinomas." (PMID 37151354, 2023). "Additionally, the urothelial carcinoma harbored elevated 5hmC at the promoter and gene body of FGFR3, which was reported to play a central role in its tumorigenesis." (PMID 36127710, 2022). "Another study of 9 patients with cervical cancer found that all of these patients had FGFR3 S249C mutations, strongly suggesting that HPV may play an important role in the development of urothelial carcinoma." (PMID 35903294, 2022). "RAS and FGFR3 mutations in urothelial carcinoma are mutually exclusive and non-overlapping events which reflect activation of oncogenic pathways through different elements." (PMID 34229750, 2021). "Activating molecular alterations in the Fibroblast Growth Factor Receptor 3 (FGFR3) gene have been identified through large-scale next generation genomic sequencing efforts across a range of tumour types including urothelial carcinoma, lung squamous cell carcinoma, glioblastoma and myeloma." (PMID 32370101, 2020).
urothelial carcinoma (continued). "The targeted therapy for FGFR3 may be used as one of the modes of treatment for urothelial carcinoma." (PMID 31528172, 2019). "Members of the ETS-family of transcription factors are downstream effectors of FGF-signalling during embryonic development but their role in urothelial carcinomas driven by FGFR3 mutation has not been investigated so far." (PMID 30952872, 2019). "In the open-label, phase II study BLC2001 presented at the 2018 ASCO Annual Symposium, erdafitinib, an oral pan-FGFR tyrosine kinase inhibitor, was tested in 96 patients with metastatic or unresectable urothelial carcinoma and FGFR alterations (mutation in FGFR3 or fusion in FGFR2 or FGFR3)." (PMID 30565086, 2019). "IHC expression of FGFR3 in high grade (HG) invasive urothelial carcinoma was positive in 18% cases, 66.7% of HG non-invasive urothelial and 82.6% of low grade (LG) non-invasive urothelial carcinomas." (PMID 31528172, 2019). "Recent studies suggest that FGFR3 is a potential therapeutic target in urothelial carcinoma (UC)." (PMID 30064409, 2018). "Despite the high mutation frequencies in urothelial carcinoma, the role of FGFR3 mutations in squamous differentiated bladder cancers is not well defined." (PMID 27669755, 2016). "This is in line with previous results of our group for FGFR3 in urothelial carcinomas." (PMID 27669755, 2016). "However, there was a reduction in the protein expression by 40.5% in RT4 cells and 46.9% in T24 cells, leading us to conclude that miR-100 plays a role in regulating FGFR3 expression in both low and high grade urothelial carcinomas." (PMID 25493074, 2014). "FGFR3 mutation is the most common phenomenon in low-grade non-invasive urothelial carcinomas, described in 70% of the cases and identified as a molecular marker of non-aggressive disease." (PMID 25493074, 2014). "A pan-FGFR inhibitor, erdafitinib, displayed a meaningful tumor response rate in patients with urothelial carcinoma, indicating that it could be especially beneficial to those with FGFR3-activated tumors, suggesting a promising targetable axis of the double-high group." (PMID 33086575, 2020). "Fusion between FGFR3 and TACC3 was also identified in glioblastoma, cervical SC and urothelial carcinoma." (PMID 39138146, 2024). "A phase I study (NCT05242822) evaluates KIN-3248 in patients with advanced tumors, including iCCA and urothelial carcinoma, harboring FGFR2 and/or FGFR3 genomic alterations." (PMID 37681152, 2023). "In urothelial carcinomas, FGFR3 was able to induce a proangiogenic phenotype, suggesting that constitutive activation of FGFR3 may be able to potentiate growth factor signalling in the tumour microenvironment and implicating FGFR3 as a potential therapeutic target from an antiangiogenic perspective." (PMID 34830836, 2021). "Other inhibitors of FGFR3 and F3T3 have also been tested in preclinical models and in trials in other tumor types, especially urothelial carcinoma and cholangiocarcinoma, for which therapeutics such as erdafitinib, rogaratinib, infigratinib, and the monoclonal antibody vofatamab have shown promise." (PMID 33168106, 2020). "The cancer type with the highest proportion of FGFR3 alterations is urothelial carcinoma with a frequency of 60–80% in the non-muscle-invasive form and 15–20% in the muscle-invasive form harbouring these molecular aberrations." (PMID 32370101, 2020).
urothelial carcinoma (continued). "Another drug, MFGR1877S, a monoclonal antibody targeting FGFR3 has demonstrated promising activity in preclinical models of urothelial carcinoma, although failed to work in clinical studies of multiple myeloma treatment." (PMID 30134556, 2018). "While it has been described that the luminal papillary subtype is enriched with FGFR3 mutations, FGFR3 copy number gain, and FGFR3 overexpression, no previous studies have searched for associations between FGFR alterations and variant histologies in metastatic/advanced urothelial carcinomas." (PMID 41097827, 2025).